SCHIP1 (schwannomin interacting protein 1)
Synonyms: SCHIP-1
Tractability: Antibody: its Gene Ontology location is reachable by antibodies, with medium confidence; the Human Protein Atlas places it where antibodies can reach.
Gene: Protein-coding gene on chromosome 3 (159,273,244 to 159,897,629, forward strand). Ensembl gene ENSG00000151967.
Subcellular location: Cytoplasm
Subcellular location (Human Protein Atlas): Cell Junctions; Cytosol; Plasma membrane; Nuclear bodies; Nucleoplasm
Gene Ontology:
Molecular function: identical protein binding; protein binding
Biological process: positive regulation of hippo signaling
Cellular component: cytoplasm; cytosol; cell junction; plasma membrane
Genetic constraint (gnomAD): Loss-of-function variants: 8 observed, 30.42 expected, observed/expected ratio (o/e) 0.26, 90% interval 0.15 to 0.47. The upper end of that interval is the gene's LOEUF score, 0.47, which puts it in group 2 of 6, group 1 being the genes least tolerant of losing a copy. Missense variants: 193 observed, 309.43 expected, observed/expected ratio (o/e) 0.62, 90% interval 0.55 to 0.7. Synonymous variants: 76 observed, 100.21 expected, observed/expected ratio (o/e) 0.76, 90% interval 0.63 to 0.92.
Homologues: Orthologues: chimpanzee SCHIP1 (99% identical), macaque SCHIP1 (96% identical), pig SCHIP1 (95% identical), mouse Schip1 (92% identical), rat Schip1 (88% identical), guinea pig SCHIP1 (85% identical), rabbit SCHIP1 (81% identical), tropical clawed frog schip1 (67% identical), zebrafish schip1 (64% identical), zebrafish SCHIP1 (36% identical), Drosophila melanogaster Schip1 (22% identical), Caenorhabditis elegans F35H12.1 (19% identical).
Diseases named in the same sentence as SCHIP1 in open-access papers:
SCHIP1 is named in the same sentence as 21 diseases in open-access papers, as found by Europe PMC text mining. Sharing a sentence is not in itself a finding about the gene and the disease. The quoted sentences say what the papers report.
colorectal cancer (2 papers, 2022). A primary or metastatic malignant neoplasm that affects the colon or rectum. "SCHIP1 also promotes the development and progression of several tumors, including adrenal tumors, acute lymphoblastic leukemia, renal cell carcinoma, and colorectal cancer." (PMID 36591215, 2022). "The results showed that the expression of S100A2, DKK3 and SCHIP1, which play a role in colorectal cancer, HNSC, and gallbladder cancer, was significantly correlated with the expression of LINC00958." (PMID 36437914, 2022).
diabetic nephropathy (1 paper, 2015). "Interaction with Nherf2 and ezrin and participation in the PDGFβ signaling axis highlights the possibility of Schip1 involvement in diabetic nephropathy, which should be the course for future functional studies of this protein." (PMID 25807495, 2015).
head and neck cancer (1 paper, 2023). A primary or metastatic malignant neoplasm affecting the head and neck. "Numerous CD-related genes have been found to be altered in head and neck cancers, such as LPP (lipoma-preferred partner), SCHIP1 (schwannomin-interacting protein 1), and IL12A (interleukin-12 subunit alpha)." (PMID 36833303, 2023).
mouth ulcers (1 paper, 2019). "Other single variant results were mirrored in the results of this analysis with increased expression of SCHIP1 increasing the odds of mouth ulcers and IL10 decreasing the odds of mouth ulcers (P = 8.99e−70 and 5.60e−55, respectively)." (PMID 30837455, 2019).
systemic sclerosis (1 paper, 2018). A chronic disorder, possibly autoimmune, marked by excessive production of collagen which results in hardening and thickening of body tissues. "SCHIP1 has been reported along with IL12A as a potential systemic sclerosis gene which functions in immune regulation via T cell activity." (PMID 30373671, 2018).
vitiligo (1 paper, 2024). Generalized well circumscribed patches of leukoderma that are generally distributed over symmetric body locations and is due to autoimmune destruction of melanocytes. "SCHIP1 (3q25) has been associated with SLE, while RNASET2(6q27) has been identified as a risk gene for both vitiligo and GD." (PMID 38616254, 2024).
cancer (4 papers, 2019 to 2025). A tumor composed of atypical neoplastic, often pleomorphic cells that invade other tissues. "SCHIP1 protein has been suggested to be involved in schwannomin activity although its function in cancer is considered as unknown." (PMID 37535601, 2023).
tumor (1 paper, 2022). "First, our results showed that there was a significant difference in the expression of SCHIP1 between the tumor and normal, and the SCHIP1 also had a poor prognosis in TCGA-AML cohort." (PMID 36591215, 2022). "SCHIP1 is located at chromosome 3q25 and is a relatively unusual protein initially discovered through interactions with the tumor inhibitor Merlin/NF2 in the mouse brain, and it is a new member of the Hippo pathway." (PMID 36591215, 2022).
SCHIP1 also shares sentences with these, for which no sentence is quoted: acute lymphoblastic leukemia (1 paper); adrenal tumors (1); atherosclerosis (1); breast carcinoma (1); clear cell renal cell carcinoma (1); diabetes (1); endothelial dysfunction (1); ependymoma (1); gallbladder cancer (1); lipoma (1); ovarian carcinoma (1); renal cell carcinoma (1); schizophrenia (1).